TNF (tumor necrosis factor)
Diseases named in the same sentence as TNF in open-access papers (continued):
Sharing a sentence is not in itself a finding about the gene and the disease.
bacterial infection (continued). "Given that M. avium is a TLR2 agonist and that Camp mRNA expression upon bacterial infection depends on TLR2 activation, our data suggest that TNF production after TLR2 stimulation by M. avium is crucial to induce murine cathelicidin expression." (PMID 25400920, 2014). "It has been believed that RNase L regulates the production of several genes such as TNF-α, IL-1β, and IFN-β during viral and bacterial infection." (PMID 24324683, 2013). "Functionally assessed to have pro-inflammatory activity in fish, IL-1β and TNF-α are often co-expressed with other macrophage-derived inflammatory mediators such as IL-8, COX-2, and iNOS in parasitic and bacterial infections." (PMID 23865616, 2013). "Previous report identified TNF as a negative regulator of Th1 type immune response during intracellular bacterial infection and showed an uncontrolled expansion of spleen CD4+ T cells, a marked increase of circulating and antigen-specific IFN-γ in TNF−/− mice." (PMID 22666310, 2012). "NF-κB is activated by various proinflammatory cytokines, such as tumor necrosis factor (TNF)-α, and viral/bacterial infection, leading to the expression of various cytokines and molecules involved in the determination of cell fate." (PMID 24212831, 2011). "TNF-α elevations were nonspecific, observed uniformly across viral, fungal, and bacterial infections." (PMID 40647525, 2025). "Clinically, CRP, TNF-α, and IL-6 are utilized to assess inflammatory responses, with CRP produced by hepatocytes in response to inflammation and TNF-α and IL-6 playing roles in immune cell activation and serving as key indicators of bacterial infection." (PMID 40005662, 2025). "They showed lower levels of serum lgG2a in response to bacterial infection, accompanied by decreased levels of chemokines, including macrophage inflammatory protein-1 alpha (MIP-1α), tumor necrosis factor α (TNFα), and Th1 cytokines such as interleukin (IL)-12." (PMID 39741341, 2025). "TNF-α can be secreted by keratinocytes in response to bacterial infection, but keratinocytes do not secrete TNF-α in response to H. ducreyi infection." (PMID 39882906, 2025). "Platelet depletion did not significantly affect systemic IL-1β, TNFα, and IL-6 levels in mice, consistent with previous findings in LPS challenge and bacterial infection." (PMID 38977927, 2024). "Serum cytokines including IL‐1β, IL‐2, IL‐5, IL‐6, IL‐8, IL‐12 p70, IL‐17, and TNF‐α were significantly higher in COVID‐19 patients with bacterial coinfections than those without bacterial infection." (PMID 39692539, 2024). "PCT is secreted by many parenchymal tissues in response to bacterial toxins, tumor necrosis factor alpha, and proinflammatory cytokines; hence, in clinical practice, PCT is recognized as a precise indicator of the severity of bacterial infection and the efficacy of antimicrobial treatment." (PMID 39797227, 2024). "This activation triggers intracellular signaling pathways, culminating in the synthesis and release of proinflammatory cytokines such as interleukins (e.g., IL-1 and IL-6) and tumor necrosis factor (TNF), which play crucial roles in the immune response against bacterial infections." (PMID 38826807, 2024). "Decreased secretion of TNF-α and IFN-γ has contributed to spontaneous bacterial infections." (PMID 36439158, 2022). "The activation of surface α-enolase trigger the production of inflammatory factors (TNFα, IL1β, IFNγ and PGE2) and could be detrimental for the pathology but could be beneficial during bacterial infection." (PMID 35154105, 2022). "When bacterial infections occur, the circulation levels of PCT increase, mainly due to the presence of bacterial endotoxins and exotoxins, as well as inflammatory cytokines, such as TNF, IL-2, and IL-6." (PMID 36553115, 2022). "In addition, MC degranulated and produced ROS, TNF-α, IL-1β, IL-6, IL-13 and MCP-1 in response to bacterial infection." (PMID 34194428, 2021).
bacterial infection (continued). "Relative gene expression and protein level of pro-inflammatory cytokines (TNF-α, IL-6, IL-8), IL-10, TLR-2 and SERT were measured in fully differentiated Caco-2 monolayers following 24 h of bacterial infection in the presence of different levels of 5-HT (0, 100, 250, 500 ng/mL)." (PMID 34799637, 2021). "In addition and supporting the role of TNF-α during γδ T cell activation, in a model of bacterial infection done by other authors, it was observed the same behavior as we found, and this may be due to the fact that γδ T cells are very sensitive to the effect of TNF-α." (PMID 34900753, 2021). "Here, we show that loss of the nuclear orphan receptor NR2F6 in germ-line Nr2f6-deficient mice enhances antigen-specific CD8+ memory formation up to 70 days after bacterial infection with Listeria monocytogenes (LmOVA) and boosts inflammatory IFN-γ, TNFα, and IL-2 cytokine recall responses." (PMID 33589606, 2021). "Bacterial infections are well known to activate p38 MAPK either directly by secreted factors and components of the bacterial cell wall or indirectly through the release of pro-inflammatory cytokines like IL-1 or TNF from activated host cells." (PMID 32788581, 2020). "In our experimental model, TNF-α secretion was essentially driven by the bacterial infection and was not further enhanced by GzmB treatment." (PMID 32151975, 2020). "Additionally, stimulation with type I Interferon, Tumor Necrosis Factor alpha (TNFα), or IFNG, cytokines that are essential for both innate and adaptive immune response to viral and bacterial infections, stimulates new i-20S." (PMID 32331228, 2020). "Whereas LPS, widely used to mimic bacterial infections in vitro, evoked distinct pro-inflammatory responses in HBMEC, expressed by mRNA and protein increases for CXCL5, IL-1α, IL-1β, IL-6, IL-8, MCP-1, MCP-3, and TNF-α, Ureaplasma spp." (PMID 31336668, 2019). "Of note, recent animal studies demonstrated that chronic hypoxemia with absent bacterial infection resulted in mildly growth restricted offspring and increased IL-6 and TNF-α in fetal sera." (PMID 31743377, 2019). "The American College of Rheumatology therefore recommend that TNF-α inhibitors should not be administered in cases of active bacterial infection or bacterial infection requiring antibiotic therapy." (PMID 31684103, 2019). "Previous studies have demonstrated that the blocking of TREM-1 signaling is associated with a reduction of inflammatory mediators such as IL-1, TNF-α, Monocyte chemoattractant protein 1 (MCP-1) and interferon (IFN)-γ and prolonged survival in mice with bacterial infection." (PMID 30832396, 2019). "We also demonstrated that in a CF background, the administration of the phage cocktail without bacterial infection, reduced TNF-α and IL-β expression to a level more similar to WT embryos." (PMID 30728389, 2019). "Approaches to enhance host immunity and for reducing bacterial infection such as adenoviral gene therapy for over production of IL-2, using TNF-α pro-inflammatory cytokine and cyclic di-GMP have shown promise in boosting immunity and reduced bacterial infections." (PMID 28979250, 2017). "Furthermore, the expression and secretion of TNF-α and IL-6 in gingival tissue was significantly decreased in LG2055-administered mice after bacterial infection." (PMID 28373699, 2017). "However, recent studies provided strong evidence for the participation of NK cells in the innate immune response to bacterial infections via the production of pro-inflammatory cytokines, such as interferon gamma (IFN-γ) and tumor necrosis factor-alpha (TNF-α)." (PMID 28706510, 2017). "As the American College of Rheumatology recommends not to administer TNF-α inhibitors to patients with active bacterial infections, our patient was instructed not to take the subsequent dose of adalimumab." (PMID 28056818, 2017).
bacterial infection (continued). "Compared with patients with other bacterial infections, those with β-haemolytic streptococcal infection had higher levels of IL-6, IL-10 and TNF-α but not a higher IL-1β level." (PMID 28176831, 2017). "In the presence of bacterial infection for example, inflammation is normally triggered, and the subsequent release of MIF allows for prolonged inflammation through the release of other pro-inflammatory cytokines like TNF-α, IL-1β, IL-6, IL-8, IL-2, and IFN-γ." (PMID 26741693, 2016). "As expected, bacterial infection greatly increased the expression of IL-6 and TNF-α in their peritoneal cavity, whereas such cytokine levels were lower or undetectable without bacterial infection." (PMID 26439699, 2015). "As a consequence, plasma TNF-α and IL-6 levels are higher in cirrhotic patients with bacterial infection than in non-cirrhotic patients." (PMID 23601847, 2013). "In contrast to the PMN TM, the migration of monocytes was significantly inhibited by bacterial infection, whereas TNFα had no influence compared to unstimulated controls." (PMID 23448224, 2013). "Thus, interleukin-1β (IL-1β), IL-6 and tumor necrosis factor-α (TNF-α), released by innate immune cells during bacterial infections, modulate feeding behavior." (PMID 20376352, 2010). "TNF-α levels were elevated in bacterial infections (46.1 pg/mL in neutropenic vs. 82.4 pg/mL in non-neutropenic patients) but demonstrated suboptimal diagnostic performance (AUC = 0.777) compared to procalcitonin (AUC = 0.875, sensitivity 94%, specificity 96.5%)." (PMID 40647525, 2025). "Upon activation by harmful stimuli such as cigarette smoke and bacterial infections, AMs release inflammatory mediators including nitric oxide (NO), prostaglandin E2 (PGE2), and pro-inflammatory cytokines such as tumor necrosis factor-α (TNF-α) and interleukin-6 (IL-6)." (PMID 35631552, 2022). "Therefore, recruited macrophages may be involved in renal injury by producing TNF-α and activating NKT/NK cells in the kidney after bacterial infections." (PMID 35008905, 2022). "Under these conditions, our inability to detect the intracellular expression of IFN-γ or very little amounts of TNF-α in CD4+ and CD8+ T cells may be in part the consequence of T cell exhaustion that has been observed before in chronic viral and bacterial infections, and in tumors." (PMID 32013893, 2020). "During the early phase of bacterial infection, NK cells mainly produce interferon-γ (IFN-γ), which can prime macrophage activation and contribute to potent innate immune responses, including the secretion of tumor necrosis factor α (TNF-α), interleukin 6 (IL-6) and interleukin 1β (IL-1β)." (PMID 33327533, 2020). "High levels of TNFα, which better represent septic or bacterial infection situations, may lead to negative effects on cells." (PMID 23110176, 2012). "We now analysed mRNA expression of these cell adhesion molecules (CAMs) under bacterial infections with the encapsulated S. suis strain 10 and its non-encapsulated isogenic mutant strain 10 Δcps in comparison to unstimulated control and TNFα-stimulated cells in the inverted Transwell system." (PMID 21592385, 2011). "Thus, there is a strong correlation between transcription factor binding at the upstream Sp1 site and transcriptional activation in response to bacterial infection but not to calcium influx among these primate TNF promoters." (PMID 17637837, 2007). "As subsequent evolution and speciation events proceeded, nucleotides involved in induction of TNF gene expression in response to bacterial infection (LPS or MTb) of monocytic cells, rather than activation of T cells, became fixed in the gibbon-orangutan and the African great ape clades." (PMID 17637837, 2007). "In the absence of PAO1 bacterial infection, to better understand if phages might induce per se an immune reaction, we measured the expression of TNF-α and IL-β in WT and CF embryos without (WT and CF) or after phage administration (WT + φ and CF + φ) at 20 hpi." (PMID 30728389, 2019).
bacterial infection (continued). "Therefore, the increased PCT levels documented in HFRS patients may be resulted from the stimuli by elevated TNF-α and IL-6 even in the absence of bacterial infection." (PMID 29868489, 2018). "The levels of TNF-α did not change neither 24 h after LPPIII administration in healthy animals, nor 24 h after bacterial infection, both in the peritoneal cavity and in the blood." (PMID 33237133, 2020). "In a mouse model of mycobacterial infection, the absence of TNF and IFN-γ leads to impaired granuloma formation and increases bacterial infection." (PMID 32411623, 2020). "As evidenced by the reduction in supernatant levels of IL-6, TNF-α, and IL-23 from CD2-a infected macrophages compared to bacterial infection without Dex, glucocorticoids appear to affect inflammatory cytokine secretion." (PMID 29867993, 2018). "We demonstrated that TNF-α secretion was downregulated in the presence of PDLF, however IL1-β production in response to bacterial infection was not significantly reduced." (PMID 28912533, 2017). "Since the potential role of other PRRs, including TLRs, for the induction of inflammatory cytokines during the bacterial infection has been reported, we examined the expression of type I IFN and TNF-α in professional phagocytic BMDMs lacking MyD88 or TRIF, the essential adaptors for TLR signaling." (PMID 30233599, 2018). "During bacterial infections, however, non-endocrine tissues such as adipocytes release large quantities of PCT into the bloodstream in response to immuno-inflammatory stimuli, including lipopolysaccharides (LPS), bacterial toxins, Interleukin-6 (IL-6), and Tumor Necrosis Factor α (TNF- α)." (PMID 40310334, 2025). "The fact that surgical intervention leads to induction of PCT by upregulation of proinflammatory cytokines such as tumor necrosis factor-(TNF-) a, Interleukin-1beta, or IL-6 may explain slight initial increase of postoperative values in absence of bacterial infection." (PMID 23766566, 2013). "Interestingly, although bacterial infection alone did not influence barrier function, TEER and paracellular TR-dextran flux were significantly affected during the process of PMN traversal under bacterial stimulation, an effect that was already observed after treatment with TNFα alone." (PMID 21592385, 2011).
cardiovascular disease (643 papers, 2005 to 2026). "Reduced levels of ADP are strongly associated with cardiovascular disease in animal models, with increased expression of anti-inflammatory genes, and suppression of pro-inflammatory gene expression (TNF α and IL-6)." (PMID 40137085, 2025). "In cardiovascular disorders, the production of adhesion molecules that cause vascular lesions is simulated by inflammatory cytokines, such as IL-1β and TNF-α." (PMID 40149874, 2025). "Despite being mechanistically linked to cardiovascular disease, TNF-α and IL-1β showed weaker and less reliable correlations." (PMID 41011058, 2025). "TNF associations with the development of cardiovascular disease and viral replication are reported in the literature." (PMID 39189824, 2024). "While steroids are associated with the development of cardiovascular disease, anti-rheumatic drugs like methotrexate, tumor necrosis factor (TNF) inhibitors, and IL-6 inhibitors have been reported to mitigate this risk." (PMID 39165751, 2024). "One study suggests a pathogenic role of the TNF system in the development of cardiovascular disease in T1DM." (PMID 38396488, 2024). "Our results will help to understand the molecular basis of TNFα-mediated induction of adhesion molecules in endothelial cells and provide insights to prevent and treat cardiovascular diseases caused by endothelial cell dysfunction." (PMID 38994453, 2024). "Mounting evidence demonstrates that TNF is a potent pro-inflammatory cytokine implicated in the pathogenesis of various cardiovascular diseases." (PMID 39024234, 2024). "Yuan supported the evidence of the causal associations of increased TNF levels with a higher risk of cardiovascular diseases, including AS." (PMID 37179331, 2023). "This indicates a favorable effect of TNF inhibitors on the cardiovascular disease risk, all the more since these markers also increase with age." (PMID 36645550, 2023). "TNF-α can cause endothelial cell apoptosis and smooth muscle cell proliferation and migration, leading to the initiation and progression of cardiovascular diseases." (PMID 37107335, 2023). "Tumor necrosis factor α contributes to the risk of cardiovascular disease by promoting platelet hyperreactivity due to reprogramming of the inflammatory, mitochondrial and metabolic pathways in megakaryocytes." (PMID 37763734, 2023). "Many case–control studies have been carried out to investigate the correlation between TNF-alpha -308 G/A polymorphism and cardiovascular disease, but the results have been equivocal." (PMID 36622512, 2023). "With these surrogate markers also increasing with aging, our findings indicate a favorable effect of TNF inhibitors on these well-established (surrogate) markers for subclinical cardiovascular disease and therefore on the cardiovascular disease risk." (PMID 36645550, 2023). "Systemic inflammation and circulating cytokines, such as interleukin 1, interleukin 6 and tumor necrosis factor α, are associated with cardiovascular diseases." (PMID 37900562, 2023). "Serum lipids and markers of systemic inflammation, such as TNF-α, are known risk factors for chronic diseases, including cardiovascular disease, one of the leading causes of death in the United States." (PMID 37571275, 2023). "Increased concentration of TNF-α in the blood is associated with an increased risk of metabolic and cardiovascular diseases." (PMID 36430593, 2022). "We aimed to evaluate the effect of tumor necrosis factor inhibitors (TNFis) on the risk of cardiovascular disease in patients with axSpA." (PMID 35698171, 2022). "There is growing evidence that IL-6 and TNF have significant inhibitory effects on myocardial metabolic processes in both ventricles, which can worsen the course of cardiovascular disease and increase the risk of tachyarrhythmia." (PMID 36059969, 2022).